SLIT2 (slit guidance ligand 2)
Diseases named in the same sentence as SLIT2 in open-access papers (continued):
Sharing a sentence is not in itself a finding about the gene and the disease.
lung carcinoma (continued). "However, 2 variants of ROBO1.IG1, 2 variants of SLIT2.D2 and 1 variant of ROBO4.IG1-2 domains in lung cancer dataset and 6 variants in SLIT2.D2 in the non-lung cancer dataset exhibits an intra-orbit amino acid position shift compared to wild types." (PMID 33318575, 2020). "Similarly, for non-lung cancer dataset, the variants conferring change in local hydrogen bond number and bond length are 50 in ROBO1, 31 in ROBO4, and 89 in SLIT2." (PMID 33318575, 2020). "To address whether lung tumor formation increases the expression of the Slit2-WT isoform, we used a Balb/c nude mice lung metastasis model via a tail vein injection of lung cancer cells." (PMID 30717252, 2019). "However, the overall expression of Slit2 was greatly reduced in the brains of mice injected with lung cancer cells." (PMID 30717252, 2019). "Therefore, there were differential expression patterns of the Slit2 isoforms between the lung cancer and pneumothorax specimens." (PMID 30717252, 2019). "However, the Slit2-WT splicing form was almost exclusively expressed in both the normal lung and lung cancer specimens in this study." (PMID 30717252, 2019). "Interestingly, the Slit2-WT isoform was almost exclusively expressed in all the lung cancer specimens and their normal counterparts, while the Slit2-ΔE15 expression was higher than the Slit2-WT expression in 40.7% of the pneumothorax patients." (PMID 30717252, 2019). "Slit2 expression is downregulated in various cancers, including lung cancer." (PMID 30717252, 2019). "Since Slit2-ΔE15, but not Slit-WT, possesses an inhibitive capability in cell proliferation, we wanted to investigate whether the expressions of the Slit2 isoforms are comparable between the normal lung tissue of lung cancer patients and healthy individuals." (PMID 30717252, 2019). "First, a high expression level of Slit2-WT is a risk factor for lung cancer, since Slit2-WT does not inhibit cell growth." (PMID 30717252, 2019). "However, the lung tumors generated via a tail vein injection of lung cancer cells decreased the Slit2-WT/Slit2-ΔE15 ratio and total Slit2 expression level." (PMID 30717252, 2019). "However, the lung tumors in mice generated via an injection of lung cancer cells into the tail vein showed a reduced expression ratio of Slit2-WT/Slit-ΔE15." (PMID 30717252, 2019). "However, an injection of lung cancer cells via the tail vein and the LPS-induced lung inflammation both decreased the Slit2 expression." (PMID 30717252, 2019). "In summary, we not only confirmed that miR-365a-3p targets and downregulates USP33 in lung adenocarcinoma, but we also further confirmed that miR-365a-3p promotes the proliferation, migration, and invasion of lung cancer cells by downregulating the USP33/SLIT2/ROBO1 pathway." (PMID 29743814, 2018). "Thus, we suggest that decreased expression of Slit2 and Robo2 genes in lung cancer may favor the migration of Schwann cells; consequently, favoring invasion by neoplastic tissue." (PMID 31921388, 2019). "Our studies showed that lung tumors generated by a tail vein injection of lung cancer cells and a LPS-induced lung inflammation decrease Slit2 expression in the lungs, while lung tumors formed in a transgenic RasG12D animal model increase Slit2 expression, mostly the Slit2-WT form." (PMID 30717252, 2019). "Our study using lung cancer samples included in TCGA database reaffirmed the results of the previous study in lung squamous cell carcinoma and also found that the levels of miR-218 and its host genes SLIT2/3 are downregulated in the tissues of lung adenocarcinoma." (PMID 28830450, 2017). "It was reported that the silence of the SLIT2/ROBO1 signaling pathway was involved in the progression of several malignancies, including gastric, pancreatic,and lung cancer." (PMID 35615148, 2022).
lung carcinoma (continued). "SLIT2 is frequently inactivated in lung cancer, and knockdown of SLIT2 decreases the interaction between beta-catenin and E-cadherin/SNAI1 in lung cancer cells, resulting in increased cell migration and reduced cell adhesion." (PMID 35053460, 2022). "Twelve of 20 genes (60%) in the list were methylation driver genes described previously in lung cancer, such as CDO1, SLIT2, SOX17 and TCF21." (PMID 33859751, 2021). "The miR-365/USP33/SLIT2/ROBO1 axis, a new mechanism, was reported to inhibit the invasion and metastasis of lung cancer." (PMID 29743814, 2018). "Our elucidation of the mechanism by which miR-365a-3p mediates the USP33/SLIT2/ROBO1 signalling pathway in lung carcinogenesis thus provides a new strategy for the diagnosis and targeted therapy of lung cancer." (PMID 29743814, 2018). "The overall concordances between gene expression ratios and methylation levels of SLIT2, MAL and IGFBP7 were 67, 89 and 78% in lung cancer cell lines." (PMID 23381221, 2013). "For example, altered epigenetic control of SLIT2 and SLIT3 has also been reported in lung cancer with hypermethylation of SLIT2 and to a lesser extent SLIT3." (PMID 20838434, 2010). "In breast and lung cancers, TSG promoter methylation SLIT2 appears to resemble TSGs such as RASSF1A, as epigenetic inactivation is more frequent than somatic mutations." (PMID 14735202, 2004). "In this study, we identified F-LT1-3, a peptide derived from the Slit2-LamG domain, which exhibits dual roles in inhibiting the proliferation and invasion of lung cancer cells but not in inhibiting the proliferation of normal cell types." (PMID 41227302, 2025). "Thus, in this study, we aimed to elucidate the role of miR-365a-3p in lung cancer cells and the relationship among miR-365a-3p, USP33, SLIT2, and ROBO1 in lung adenocarcinoma." (PMID 29743814, 2018). "It has been reported that the USP33/SLIT2/ROBO1 signalling pathway inhibits the migration of cancer cells; therefore, we hypothesised that miR-365a-3p downregulates this pathway to promote lung cancer progression." (PMID 29743814, 2018). "The re-expression of SLIT2, MAL and IGFBP7 that was observed in lung cancer cell lines after treatment with a demethylating agent exhibited good concordance with the methylation status, suggesting that expression of those genes was downregulated mainly by hypermethylation." (PMID 23381221, 2013). "However, it has not been reported in lung cancer yet, although hypermethylation of SLIT2 and SLIT3 has been reported in lung cancer." (PMID 35053460, 2022). "Since the Slit2-ΔE15 splicing form, but not Slit2-WT, is able to inhibit the growth of cancer cells, a higher ratio of Slit2-WT/Slit-ΔE15 expression in the tumor microenvironment is more favorable for the development of lung cancer than a lower ratio of Slit2-WT/Slit-ΔE15 expression." (PMID 30717252, 2019).
glioma (29 papers, 2004 to 2025). A benign or malignant brain and spinal cord tumor that arises from glial cells (astrocytes, oligodendrocytes, ependymal cells). "It was further shown that Slit2-associated inhibition of glioma cell invasion was mediated through a blockade of Cdc42’s Rho GTPase activity, without any alterations in N-cadherin and β-catenin expression levels." (PMID 39456164, 2024). "In control healthy brain cells, the expression of Slit2 reaches the highest level, while its expression is decreased in high-grade gliomas." (PMID 40149733, 2025). "Preliminary studies have indicated significant differences in the expression of Slit2 and Robo1 between healthy brain cells and glioma cells." (PMID 40149733, 2025). "The angiogenic potential of Slit2 in human glioma cells was studied by implanting tumor cell spheroids via the cranial windows into tomato-fluorescence reporter mice." (PMID 39456164, 2024). "The glioma arteries that overexpressed Slit2, on the other hand, were dilated and lost branchpoints sooner." (PMID 39456164, 2024). "In summary, it is evident that Slit2 activity is involved in cell migration and the invasion of glioma cells mediated primarily through Robo1." (PMID 39456164, 2024). "Regarding gliomas, initial studies have shown that Slit2 and Robo1 expression differs between healthy brain cells versus glioma cells." (PMID 39456164, 2024). "It has been proved that SLIT2/ROBO1 signaling inhibits glioma cell migration and invasion by inactivation of Cdc42-GTP." (PMID 38279111, 2024). "Slit2 expression is highest in control healthy brain cells and decreases in high-grade gliomas, and is therefore considered as a tumor suppressor." (PMID 39456164, 2024). "On the other hand, Slit2 knockdown in mouse glioma cells and patient-derived GBM xenografts decreased tumor growth and increased treatment resistance." (PMID 36497269, 2022). "On the one hand, Slit2 expression is suppressed in glioma cells and intracranial mice xenografts with forced expression hampering glioma cell migration and invasion." (PMID 36497269, 2022). "Specifically, SLIT2 has been shown to suppress glioma cell invasion and motility as evidenced by the reduction of SLIT2 expression in GBM." (PMID 34012965, 2021). "In the case of brain damage, Slit2 is expressed by glial cells in addition to neurons, such as in glioma or epilepsy." (PMID 33613201, 2020). "Slit2 expression was also down-regulated in grade III–IV glioma tissues, and the viability, migration and tube formation of ECs were significantly reduced in the Robo4 overexpression group that was pretreated with exogenous Slit2." (PMID 31160487, 2019). "Accordingly, Robo4 inhibits glioma-induced EC proliferation, migration and tube formation by binding to its ligand Slit2, and thus, the first Robo4 targeting strategy is the injection of high doses of the recombinant Slit2 protein." (PMID 31160487, 2019). "A frequently occurring Slit2 deactivation through hypermethylation of CpG islands in the promoter region has been observed in glioma cell lines and in glioma tumors." (PMID 29864155, 2018). "In glioma and esophageal cancer, negative regulation of Slit2 on Cdc42 and cell migration also had been reported, suggesting Cdc42 a common key target of the Slit2-Robo1 signaling in human cancers." (PMID 27923383, 2016). "Previous reports have indicated a clear association between the Slit2 expression and tumor invasion in several cancer types, including CRC, glioma, and skin cancer." (PMID 25605242, 2015). "The signaling between Slit2 and its binding partner, Robo 1, inhibits glioma cell migration in vitro and in vivo by inactivating CDC42-GTP, a Rho GTPase which induces the complexing of WASp and the Arp2/3 complex with actin to promote podosome formation." (PMID 23119100, 2012).
glioma (continued). "A number of studies have demonstrated that SLIT2 is epigenetically silenced by hypermethylation of the promoter region in a broad spectrum of other tumors, such as lung, breast, glioma, colon, and cervical cancers, leading to inactivation of SLIT2 expression." (PMID 22140553, 2011). "It has been published that Slit2 has a repulsive function towards glioma cells, which is mediated by the Robo1 receptor." (PMID 20298552, 2010). "Slit2-Robo1 signaling facilitates glioma cell migration and is involved in angiogenesis by increasing microvessel density and tumor mass in a tumor xenograft model." (PMID 20300657, 2010). "Three human Slit gene orthologues have been characterised and recently we reported frequent promoter region hypermethylation and transcriptional silencing of SLIT2 in lung, breast, colorectal and glioma cell lines and primary tumours." (PMID 15534609, 2004). "Moreover, this study showed that although both glioma and medulloblastoma tumor cells express Slit2 and Robo1, the recombinant Slit2 protein inhibited only medulloblastoma invasion." (PMID 39456164, 2024). "Notably, when SLIT2 was knocked down in glioma cells, or its systemic inhibition was achieved through an SLIT2-trapping protein (ROBO1Fc), it prevented the tumor-promoting polarization of TAMs and the expression of angiogenic genes." (PMID 38275876, 2024). "Following these original observations, recent studies employing murine GBM models or patient-derived tumor spheres and xenograft models demonstrate contradictory results, with the increased expression of Slit2 in gliomas being correlated with tumor progression and invasiveness." (PMID 39456164, 2024). "Furthermore, Robo1 knockdown in glioma cells reversed the chemorepulsive effects of Slit2, confirming that Robo1 serves as the main Slit2 receptor." (PMID 39456164, 2024). "Moreover, both Robo1 and Robo2 expression were detected in tumor cells, suggesting that Slit2 effects in glioma angiogenesis were mediated through these receptors." (PMID 39456164, 2024). "A possible target for glioma prevention and treatment is Slit2/ROBO1 signaling." (PMID 38137332, 2023). "Furthermore, recent studies have suggested that the Slit2/Robo1 signaling might be enlisted for treating glioma because it can inhibit glioma cell migration." (PMID 25299227, 2014). "In addition deletion or methylation mediated deregulation of SLIT2 has already been reported in various malignancies including gliomas, neuroblastoma, Wilm’s tumor, leukemia and carcinomas of lung, breast, kidney, colon etc though, none reported the stage wise correlation pattern." (PMID 22719878, 2012). "In highly invasive human glioma U87MG Ang2-expressing cells, Slit2 expression was involved in the inhibition of cell migration as well as tumor cell infiltration into the brain parenchyma in vivo." (PMID 39456164, 2024). "SLIT2/ROBO2-mediated PI3K-γ activation accelerated microglia/macrophage chemotaxis and tumor-supportive polarization, thus enhancing macrophage invasion and diminishing efficacy of chemotherapy and immunotherapy in gliomas." (PMID 36998443, 2023). "In gliomas, Slit2 and its transmembrane receptor ROBO1 have various distribution patterns; in contrast to ROBO1, which is highly expressed in many grades of gliomas at both the mRNA and protein levels, Slit2 is weakly expressed in pilocytic astrocytoma, fibrillary astrocytoma, and glioblastoma." (PMID 38137332, 2023). "It was demonstrated that Slit2/ROBO1 signaling prevented glioma cell motility and invasion by inactivating Cdc42-GTP, even though the precise mechanisms behind this tumor-suppressive gene impact of Slit2/ROBO1 remain unknown." (PMID 38137332, 2023). "Therefore, the miRNA network upstream of SLIT1 and other possible miR-640 targets (e.g., SLIT2 and SLIT3 mRNAs) related to glioma radiation resistance requires further exploration." (PMID 35996510, 2022).
colorectal cancer (25 papers, 2004 to 2025). A primary or metastatic malignant neoplasm that affects the colon or rectum. "Another plausible mechanism is from Slit2-mediated anti-tumoral function in colorectal cancer cells, where both SLIT2 and ROBO are downregulated." (PMID 36361532, 2022). "Our previous study reported that the higher expression of SLIT2 in cancer tissue of colorectal carcinoma promotes tumor metastasis." (PMID 32760720, 2020). "Slit2 (slit guidance ligand 2), a ligand of the Roundabout1 (Robo1) transmembrane receptor, is often overexpressed in colorectal carcinomas (CRCs)." (PMID 31242633, 2019). "In colorectal carcinoma cells, Slit2/Robo1 signaling promotes degradation of E-cadherin, EMT, tumor growth and metastasis." (PMID 29141914, 2018). "Robo4, a receptor for Slit2, is highly expressed in solid tumors, including brain, lung, urinary bladder and colorectal cancers and its expression is restricted to tumor vasculature but down-regulated in mature vasculature." (PMID 25794001, 2015). "Previously, they have reported elevated expression of SLIT2 in human colorectal carcinoma tissues and cell lines." (PMID 26674478, 2015). "In colorectal carcinoma patients, the overexpression of SLIT2 and ROBO1 was significantly associated with an increased metastatic risk and poorer overall survival in colorectal carcinoma patients." (PMID 26674478, 2015). "Although the involvement of Slit2/Robo1 signaling in tumor development has been widely implicated, the biological significance and molecular mechanisms of Slit2/Robo1 signaling in the initiation of colorectal carcinoma are largely undetermined." (PMID 25605242, 2015). "They examined the role of SLIT2 as a tumour suppressor in a panel of 32 colorectal cancers, finding that 23 (72%) were methylated in this region." (PMID 23671423, 2013). "The conditioned medium from SLIT2-transfected cells reduces cell growth and induces apoptosis of colorectal carcinoma cell lines, implicating that SLIT2 has tumor-suppressor activities." (PMID 22140553, 2011). "As SLIT2 has been shown to inhibit cell migration of colorectal cancer cells, we wanted to analyze whether supplementing ddR1 + R2 cell cultures with SLIT2 recombinant protein would affect the enhanced mobility of the ddR1 + R2 cells." (PMID 38630262, 2024). "For example, an abnormal dopaminergic commissure at the level of the diencephalon traveling through the hypothalamus from the MFB has been previously reported in the Slit1/Slit2 double KO, the Deleted in colorectal cancer (Dcc) KO, and the NK2 Homeobox 1 (Nkx2.1) KO mice." (PMID 27648578, 2016). "We previously showed that Slit2-Robo1 inhibit cell migration in colorectal cancer (CRC)." (PMID 27923383, 2016). "This led us to speculate that the Slit2/Robo1 signaling pathway may likely regulate Wnt/β-catenin signaling and thereby promote the initiation of colorectal carcinoma." (PMID 25605242, 2015). "The coincidental activation of Slit2/Robo1 signaling and Src in colorectal carcinoma led us to hypothesize that a potential interaction between the Slit2/Robo1 and Src signaling may be an important mechanism involved in the activation of Wnt/β-catenin signaling." (PMID 25605242, 2015). "Further investigation into the genomic location of miR-218-5p, embedded within the SLIT2 and SLIT3 introns on chromosome 4 and chromosome 5, respectively, revealed epigenetic silencing through promoter hypermethylation in colorectal cancer cell models." (PMID 40362385, 2025). "Furthermore, Slit2 and Robo1 promote degradation of ECad and expression of EMT markers in human colorectal carcinoma cell lines, suggesting that this regulation is conserved between flies and mammals." (PMID 33968921, 2021).
colorectal cancer (continued). "Here, we employed several complementary mouse models of intestinal cancers, including the Slit2 transgenic mice, the ApcMin/+ spontaneous intestinal adenoma mouse model, and the DMH/DSS-induced colorectal carcinoma model to clarify function of Slit2/Robo1 signaling in intestinal tumorigenesis." (PMID 25605242, 2015).